CD4 (CD4 molecule)
Diseases named in the same sentence as CD4 in open-access papers (continued):
Sharing a sentence is not in itself a finding about the gene and the disease.
tumor (continued). "However, there was a significant correlation of CD8 and CD4 positive T cells within the tumour nest and the “NFκB on” subgroup." (PMID 26943587, 2016). "Notably, B16-OVA tumor cells that were incubated either with CD4+ or CD8+ T cells, previously primed with desialylated OVA-pulsed sDCs, showed significantly less viability than those incubated with T cells primed with fully sialylated OVA-pulsed sDCs." (PMID 27203391, 2016). "This may explain results seen in this manuscript including increased NK and CD8+ T cell function, changes in CD4+ T cell recruitment, reduction in immune inhibitory receptor expression, and ligand availability on the tumor cells themselves." (PMID 27178315, 2016). "However, we did not observe any global differences in the expression of IFN-γ by CD4 or CD8 T cells in tumor versus adjacent uninvolved tissue." (PMID 27014625, 2016). "Alternatively, depletion of CD4+ T cells could decrease tumor infiltrating CD4+ Treg cells and thus foster the activity of tumor infiltrating CD8+ T cells." (PMID 27057460, 2016). "However, the number of spleen-derived TGF-β+CD4+Foxp3+ T cells increased compared with WT, with the exception of the tumor and spleen." (PMID 27075020, 2016). "Therefore, both CD8+ CTL/Treg ratio and CD4+Teff/Treg ratios were greatly enhanced in secondary tumours of mice after PLGA-ICG-R837-based PTT plus anti-CTLA-4 treatment." (PMID 27767031, 2016). "As for the correlations with positive cell infiltration, we observed that higher levels (above the median) of CD4+ cells in the tumor stroma correlated with epidermal growth factor receptor (EGFR)-mutated patients (p = 0.047) and with ADC histology (p = 0.030)." (PMID 27463005, 2016). "Another option may be to boost paracrine activity of infiltrating CD4+ effector cells reinforcing senescence or NK-cell mediated clearance of senescent tumor cells." (PMID 26657295, 2016). "Intraperitoneal administration of a recombinant VSV variant targeted to Her2/neu-expressing tumours, followed by systemic CTLA-4 blockade one day later, elicited a potent anti-tumour CD4+ and CD8+ T cell response in immunocompetent mice bearing Her2/neu-positive D2F2/E2 murine mammary tumours." (PMID 26751469, 2016). "Similarly, we detected increased PD-1 expression on CD4+Foxp3- TILs isolated from α-CTLA-4-treated MB49 tumour-bearing mice." (PMID 27498556, 2016). "RNA expression of CCL21 was analyzed in 18 primary therapy-naïve tumor samples, and the expression levels were correlated with the immunohistochemical staining of the CD4+- and CD8+-infiltrating T cells in eight tissue samples for which sufficient FFPE material was still available." (PMID 27369431, 2016). "Importantly, HRS cells account for only about 1% of cells in the tumor tissue and the majority of cells in classical HL are a mixed immune infiltrate comprising of CD4+ cells." (PMID 27588406, 2016). "To explore the mechanisms underlying the loss of CD4+ T cell-dependent tumor control in non-responder mice, we examined several aspects of the CD4+ T cell response." (PMID 27121060, 2016). "As such, being able to increase MHCI and/or MHCII levels pharmacologically on tumor cells would be an attractive complement to CD4/CD8-based immunotherapy because CD4- and CD8 T cell responses are functionally influenced by the pMHC density present at the cell surface." (PMID 27729860, 2016). "In this study, we could define tumor infiltrating Tregs in detail as CD45+CD4+CD25± and FOXP3+ cells and found that a higher frequency of Tregs among total examined cells was associated with a longer OS, and this result is in line with several prior reports." (PMID 26799288, 2016). "A strong isotype-switched anti-tumor antibody response was produced in response to cognate CD4+ T cell help, with large increases in the serum levels of IgG1, IgG2c (the functional equivalent of IgG2a, which is not present in C57BL/6 mice) and IgG2b, and smaller increases in IgG3, IgA and IgE." (PMID 27121060, 2016).
tumor (continued). "A previous study demonstrated a strong synergistic activation of HIV-1 production by clinically used HDACIs including VOR combined with the non-tumor-promoting NF-κB inducer prostratin in latently infected cell lines and resting CD4+ T cells isolated from cART-treated patients." (PMID 27769267, 2016). "We observed almost identical results when measuring tumor-derived CD4+Foxp3+ T cells." (PMID 27075020, 2016). "Moreover, this case can result in prime CD8+ and CD4+ cells that are related to efficient tumor inhibition." (PMID 27246873, 2016). "However, no previous publications have evaluated prognostic performance of circulating tumor cells and CD4+CD25+Foxp3+Tregs." (PMID 27439521, 2016). "The statistical results showed that the fluctuation of CD4/CD8 cell ratios during tumor progression after vaccination was significant and may reflect more rigorous and dynamic immune regulation and activity in the Treatment group (Fig. 3Aa and Bc)." (PMID 27669687, 2016). "Therefore, CD4+ T cell activation by DC-tumor FCs through MHC class II interactions plays an essential role in the induction of effective antitumor immunity." (PMID 27240347, 2016). "The shifted cytokine profiles of T cells and CD4/CD8 ratio after actein treatments might also play role in regulating the tumor progression." (PMID 27731376, 2016). "In addition to enhancing responses of CD8+ T cell responses, CD4+ mediate tumor rejection through cytotoxic effect on tumor cells, up regulation of MHC molecules expression, inhibition of angiogenesis and induction of tumor dormancy." (PMID 27401917, 2016). "In HCC, circulating and tumor-infiltrating CD4+ cytotoxic T cells are increased in early stages of HCC but are decreased in advanced stages; loss of CD4+ cytotoxic T cells is significantly correlated with high mortality rate and reduces survival time of HCC patients." (PMID 27136203, 2016). "Based on the potent immunoregulatory function these cells have on immune responses and inflammation, it is reasonable to conceive that Foxp3+CD4+ T cells may in fact help prevent or delay inflammation-mediated tumor development." (PMID 26604855, 2015). "Together, these results implicate that STAT3 ablation results in a considerably different tumour microenvironment composed of more myeloid cells, increased CD4+/CD8+ lymphocyte ratio and enhanced angiogenesis in our murine as well as in the human AC xenograft models." (PMID 25734337, 2015). "Importantly, besides the increase in numbers, the cell subsets of CD4+ T cells also dynamically changed, indicating distinct functions of CD4+ T cells in the different tumor developing stages." (PMID 25968569, 2015). "For this purpose, we first identified the candidate chemokines that could facilitate recruitment of CD4+ T cells into the tumour mass." (PMID 25495686, 2015). "Thus, the tumor microenvironment in Apc/Min+ mice have markedly increased numbers of Foxp3+ Tregs but only moderately increased IL-17A+ CD4 T cells in the LP, suggesting that Apc/Min+ Foxp3+ Tregs are altered in the LP." (PMID 26146642, 2015). "A number of reports support the essential role of CD4+ T cells in the anti-tumor responses due to their ability to stimulate dendritic cells and potentiate anti-tumor immune response by enhancing antigen presentation and to the contribution to the memory response establishment." (PMID 25849072, 2015). "Thus, the anti-tumor effect of Loxoribin is elicited via rendering CD4+CD25−T cells refractory to the suppressive effect of Treg cells." (PMID 25593198, 2015). "Certain drugs [e.g., anti-VEGFR2 monoclonal antibody, sunitinib] destroy tumor blood vessels and trigger immune response by increasing the levels of CD4+ and CD8+ T lymphocytes, as well as by inhibiting the activity of immunosuppressive Treg or myeloid-derived suppressor cells (MDSC)." (PMID 25801067, 2015).
tumor (continued). "Moreover, tumor cells stimulated by Ara-C induced CD4+ T cells to produce more IL2 (290.6 ± 33.5 pg/ml) than tumor cells alone (p < 0.01)." (PMID 26444983, 2015). "Moreover, a significantly higher frequency of CD4+ T cells expressing CXCR3 was found in the tumours compared with NDLN." (PMID 25495686, 2015). "To determine whether CD4+ TIL155 recognized specific tumor antigens, we generated 31 T cell clones by a limiting dilution method." (PMID 25993655, 2015). "In the tumor microenvironment, Tregs cells could inhibit the proliferation of tumor cells to exert an antitumor effect through suppressing CD4 + T cells and CD8 + T cell activation." (PMID 26064167, 2015). "Additionally, a high percentage of CD4+ T-cells positively correlates with tumor stage and metastasis." (PMID 25884510, 2015). "The stimulated CD4+ Th cells could also provide cognate help to CD8+ T cells to generate a more robust anti-tumor immunity and long-term memory." (PMID 26343191, 2015). "The antitumour effects of CD4+ T cells might be exerted through other host-derived components such as tumour-specific CD8+ T cells." (PMID 25850032, 2015). "All four T cell clones were CD4+ T cells and recognized autologous 155mel tumor cells." (PMID 25993655, 2015). "In addition, we also measured the expression of CCR4, CCR5 and CXCR3 receptors on tumor infiltrating CD8+ and CD4+ T cells from both WT and KO mice and found AMPK deficiency had no overt impact on the expression of these major chemokine receptors." (PMID 25760243, 2015). "As CD4+ T-cells comprise a heterogeneous group in that there are both tumor-reactive and suppressive populations, we set out to examine whether concomitant high Foxp3+ T-cell density contributed to its association with high-PD-L1-expressing metastases." (PMID 26317902, 2015). "In the present study, we asked whether CD4+ T-cell dysfunction in aged hosts could be reversed by complementation with young tumour-specific CD4+ T cells." (PMID 25850032, 2015). "Daclizumab is used to treat acute-graft rejection by targeting CD25-expressing effector T cells, but it has also been shown to effectively deplete CD4+ regulatory T cells in humans, improving immune responses after tumor-antigen vaccination in patients with metastatic breast cancer." (PMID 28210682, 2015). "Interestingly, 2-DG prevented tumor-induced augmentation of CD4+CD25+ T-reg cells in tumor bearing mice (4.07% ± 0.41%; p < 0.001 and 4.89% ± 0.55%; p < 0.01 in 0.2% and 0.4% 2-DG group respectively compared to 7.74 ± 0.95 in control)." (PMID 26135741, 2015). "In addition, it has been shown that IFNγ+-secreting IL-17+ CD4+ T cells are increased in inflamed tissues and, importantly, have been reported to mediate tumor regression in a mouse model via an IFNγ- dependent mechanism." (PMID 26176858, 2015). "The role of CD70-mediated immune escape was also demonstrated in non-small cell lung cancer (NSCLC), where CD27+ lymphocytes were found in the tumor microenvironment with a trend towards increased Foxp3 expression and higher CD4/CD8 ratios surrounding CD70+ tumor cells." (PMID 26605342, 2015). "Additionally, in the GL261 model, the CD4+ T cell compartment has been shown to contribute to anti-tumor immunity through promotion of Th1 and Th17 differentiation, but also serve a suppressive role through the activity of regulatory T cells." (PMID 25933216, 2015). "Importantly, when tumor-specific CD4+ T cells are adoptively transferred into mice orthotopically injected with 4T1 tumor cells, tumor colonization to bone, but not to other metastatic sites, is increased." (PMID 26000310, 2015). "Since APCs within the tumor microenvironment are frequently suppressive, activation of conventional non-tumor-recognizing CD4+ T cells and therefore the provision of CD4-help may be limited at the local tumor site." (PMID 26447332, 2015).
tumor (continued). "Nevertheless, protective cellular immunity against transplantable murine SV40 tumors can be achieved by pre-immunization with SV40 or purified T-Ag, which induces an efficient and long-lasting CD4+ helper T-cell dependent CTL response against established SV40 tumor cells (e.g. mKSA)." (PMID 26513294, 2015). "In view of these findings, we proceeded to test whether the HER-3872−886 peptide itself could induce antigen-specific, tumor-reactive CD4 T cells." (PMID 26538233, 2015). "Previous investigation of the peripheral blood lymphocyte membrane phenotype of anti-Hu antibody syndrome patients has demonstrated that CD4+ T cells can directly attack the HuD antigen and are involved in cell-mediated nervous system damage and anti-tumor effects." (PMID 25412252, 2015). "In the present study we could verify that not only cytotoxic CD8+ T cells are involved in r28M-mediated tumor cell killing but also CD4+ cells." (PMID 26469402, 2015). "CD4 T cells orchestrate a broad range of immune responses and are equipped to differentiate into multiple sublineages, which can induce and maintain immune responses against tumor antigens." (PMID 26350591, 2015). "To determine whether circulating IL-6 influences the ability of CD4+ T cells to control tumours, we employed IL-6 blockade combined with OT-II cell transfer." (PMID 25850032, 2015). "CD4+ T cells play a central role in regulating all antigen-specific immune responses, and a role in both the induction and the effector phases of the anti-tumor response." (PMID 25801067, 2015). "Furthermore, the CD4+ T cell subsets among the TILs were examined to gain insight into immune regulation in the tumor microenvironment." (PMID 25826093, 2015). "Interestingly, CTLA-4 levels and the percentages of tumor infiltrating CD4+Foxp3+ Tregs remained unchanged." (PMID 25851535, 2015). "As intra-tumor infiltrating T cells, peripheral blood of CD4+CD25+ T cells could be regarded as an alternative biomarker to predict the clinical outcomes among whom exposure to DC-CIK infusions, especially among early stage and TNBC patients." (PMID 26462021, 2015). "Tumor infiltrating CD4+, CD8+ T cells were associated with neither overall survival nor disease-free survival." (PMID 26604855, 2015). "TGF-β-induced immunosuppression occurs when tumor cells escape attack by the immune system through various mechanisms, including interaction with CD4+CD25+Foxp3+ regulatory T cells (Treg cells), tumor-associated macrophages, tumor-associated neutrophils (TAN), and T helper 17 (TH17)." (PMID 26779375, 2015). "The proportion and total number of proliferating CD8+ T cells increased similarly following tumor injection in control and CD4-cre x IKKβfl/fl T cells, indicating that the initial T cell priming and cell survival following tumor implantation occurred normally despite lack of T cell-IKKβ." (PMID 25648675, 2015). "However, T cell responses are typically inhibited in tumour immunity, especially in effector CD4+ T cells (Th1, Th2 and Th17 responses)." (PMID 25651850, 2015). "However, CD4+ T cells more rapidly infiltrated into the tumor sites than CD8+ T cells with the tumor progression, and therefore became the more dominant population in late stages of tumor development." (PMID 25968569, 2015). "In contrast, most labelled CD4+ T cells recovered from the tumour were from CXCR3−/− animals." (PMID 25495686, 2015). "Tumor recognition by CD4+ T cells was HLA-DP restricted and NY-ESO-1 specific." (PMID 26447332, 2015). "An alternative path by which tumor antigen-specific CD4+ T cells could overcome the requirement for APCs within the tumor microenvironment is to directly recognize cancer cells." (PMID 26447332, 2015). "However, animal models have routinely suggested that CD4+ T cell help is essential for effective anti-tumor immunity." (PMID 25901284, 2015).
tumor (continued). "Increases in serum IL-10 levels, and tumor-infiltrating CD8+ T cells, and decreases in PBMC CD4+ populations after NHS-IL12 treatment were linked to exposure and may be evaluable as biomarkers in the future." (PMID 26091536, 2015). "RNAs offer similar advantages as the whole tumor cell lysate; this form of therapy has no HLA-restriction, multiple tumor-associated antigens can be targeted at the same time, and both CD4+ and CD8+ T cell responses can be elicited via DCs." (PMID 26343191, 2015). "In addition, chimeric antigen-receptor transduced CD4+ T cells showed potent anti-tumor immune responses." (PMID 26447332, 2015). "Ex vivo studies of NHL patient samples revealed that direct cell contact with tumor cells induced differentiation of autologous PBMCs into CD4+CD25+FoxP3+ Tregs that were found to be directly responsible for effector T cell hyporesponsiveness by in vitro depletion experiments." (PMID 25941795, 2015). "However, mRCC patients are immunosuppressed due to local and systemic influences of the tumor cells and display both DC and CD4+ helper T cell dysfunction." (PMID 25901286, 2015). "Moreover, pan HER-family tyrosine kinase inhibitor augmented the responses of HER-3-reactive CD4 T cells via upregulation of HLA-DR protein on the surface of tumor cells." (PMID 26538233, 2015). "However, vaccine strategies that directly enhance the priming of tumor-specific CD4+ T-cells have been shown to augment the systemic rejection of MHC class II negative tumors." (PMID 26673159, 2015). "This role as a transcriptional regulator could influence the presentation of tumor-related antigens to CD4+ T cells and thus contribute to adaptive immune responses targeting tumor cells." (PMID 26425120, 2015). "Vigorous progression of pulmonary metastatic tumour was prevented in young mice when either IFN-γ-sufficient or -deficient CD4+ T cells were transferred, whereas vaccinated aged mice failed to suppress the tumour outgrowth." (PMID 25850032, 2015). "Multiple studies now indicate that CD4+ T-cells enhance the anti-tumor response of CD8+ T-cells." (PMID 25690042, 2015). "In our study, in addition to general analysis of tumor-infiltrating lymphocytes, analysis of specific T-cell subsets demonstrated a significant increase in tumor-infiltrating T helper cells (CD4+) as well as cytotoxic T cells (CD8+) compared with healthy donor lungs." (PMID 26413839, 2015). "In the current study, tumor regression was most effective with both CD4 and CD8 cells." (PMID 26090481, 2015). "Although CD4+ or CD8+ T cells may be required for an optimal anti-tumor response, the loss of NK cells resulted in a more profound defect in tumor immunity." (PMID 25674087, 2015). "However, activation of antigen-specific CD4+ T cells is restricted at local tumor sites where antigen-presenting cells (APCs) are frequently dysfunctional, which can cause rapid exhaustion of anti-tumor immune responses." (PMID 26447332, 2015). "Since TRP-1 is a tumor-associated antigen, it is possible that pre-mNK cells could perceive TRP-1-specific CD4+ T cells to be autoreactive." (PMID 26405570, 2015). "MHC II presents tumor antigens to CD4+T helper cells, leading to cellular mediated immune response." (PMID 26161392, 2015). "Recently, a study reported that cancer cells pre-treated with paclitaxel and doxorubicin could enhance cancer-specific CD4+ T cell production and thus induce significant apoptosis and a therapeutic anti-tumor immune response in a mouse model." (PMID 26673159, 2015). "Also, a threefold increase of tumor-infiltrating CD4+ T cells and a twofold increase of CD8+ T cells, respectively, were observed as compared to monotherapy." (PMID 25801067, 2015). "Finally, NKp46, CD8 and CD4 levels were significantly higher in mammary glands of 26-week-old vaccinated mice with respect to the tumor area of untreated 26-week-old mice." (PMID 25997501, 2015).